BRCA1 (BRCA1 DNA repair associated)
Diseases named in the same sentence as BRCA1 in open-access papers (continued):
Sharing a sentence is not in itself a finding about the gene and the disease.
breast cancer (continued). "For sporadic breast cancer, particularly for the triple negative sub-type, we also need to identify BRCA1-inactivating mutations in tumors." (PMID 31413819, 2019). "Ductal carcinoma in situ (DCIS) is considered a component of the clinical spectrum of breast cancer even in those with BRCA1/2 mutation." (PMID 30652428, 2019). "Triple-negative breast cancer (TNBC) is a highly aggressive form of breast cancer that has a high mortality rate and disproportionately affects young African American (AA) women who carry mutations in the BRCA1 gene." (PMID 33860286, 2019). "Overall, BRCA1/2 mutations account for one in four patients with a family history of breast cancer/breast and ovarian cancer, one in five patients with male breast cancer, and one in eight patients with early-onset breast cancer." (PMID 31528241, 2019). "Genetic testing for germline mutations in BRCA1/2 of patients with breast cancer (BC) is part of routine patient care." (PMID 30982232, 2019). "Inherited mutations of BRCA1 increases the lifetime risk of developing breast cancer from 11% in the general population to 50–80% and ovarian cancer from 1.4–2.5% to 15–60%." (PMID 31771139, 2019). "The tumor suppressor gene BRCA1 is frequently mutated in human cancers including breast cancer, ovarian cancer and prostate cancer." (PMID 31273285, 2019). "The available literature does not, however, provide any information on the relationship between the BRCA1 mutation, incidence of breast cancer and salivary antioxidants, oxidative damage and the secretory function of salivary glands." (PMID 31597313, 2019). "Other studies have also shown that there are higher frequencies of BRCA1 mutations in breast cancer patients of African descent, especially descendants with an origin of ancestry from Nigeria and the Bahamas." (PMID 33860286, 2019). "Fewer differences were detected in the comparisons between the eight PALB2-associated breast cancers with mono-allelic inactivation (two ER−/HER2− and four ER+) and the 683 ER−/HER2− and ER+non-BRCA1/2/PALB2-associated breast cancers." (PMID 31428676, 2019). "Five of the 26 individuals with BRCA1 or BRCA2 mutations were diagnosed with primary breast cancer while undergoing surveillance." (PMID 30980249, 2019). "In this nationwide cohort study, we observed lower overall and breast cancer-specific mortality rates among BRCA1 mutation carriers opting for BRRM than among those under surveillance." (PMID 31302855, 2019). "The objective of this study was to investigate the spectrum of BRCA1/2 genetic variants and estimate their frequencies in familial breast cancer." (PMID 31131559, 2019). "The great success of PARPi in preclinical and clinical studies propels the approval of four PARPis for BRCA1/2 mutated ovarian and breast cancer patients." (PMID 31737426, 2019). "Of 78 total patients, 15 had BRCA1 mutation-associated breast cancer and 12 had BRCA2 mutation-associated breast cancer." (PMID 30934991, 2019). "In contrast to studies reporting BRCA1/2 prevalence for a subset of high risk women, the present sample reflects the general breast cancer population." (PMID 30175445, 2019). "Using only the receptor triple negativity as a selection criterion allowed us to identify 25% (2/8) of BRCA1 mutation carriers with a family history of breast cancer." (PMID 30975216, 2019). "Pathogenic variants associated with hereditary breast cancer have been reported for BRCA1 and BRCA2 (BRCA1/2) genes in patients from multiple ethnicities, but limited information is available from sub-Saharan African populations." (PMID 31060517, 2019). "Our main goal was to screening of new mutation in BRCT domain of BRCA1 gene in patients with familial breast cancer." (PMID 30806067, 2019).
breast cancer (continued). "For instance in breast cancer, a women can inherit a BRCA1/BRCA2 mutation, which gives her a life-time elevated risk of breast cancer of 50–85%." (PMID 30781705, 2019). "There was a marked increase in AGE in patients with the BRCA1 mutation and suffering from breast cancer." (PMID 31597313, 2019). "Our results suggest that there are challenges involved in the early detection of breast cancers in BRCA1 or BRCA2 mutation carriers." (PMID 30980249, 2019). "Poly(ADP-ribose) polymerase (PARP) inhibition is used in the clinic to kill HR-deficient tumor cells such as cells mutated for the breast cancer predisposition genes BRCA1 or BRCA2 by synthetic lethality." (PMID 31584931, 2019). "Previous translational investigations have suggested an increase in stromal TILs and a higher tumor mutational burden in BRCA1 mutation-associated breast cancer." (PMID 31336685, 2019). "In a large collection of families with hereditary breast cancer (n=237), 52% of families had disease that was likely attributable to mutations in BRCA1 while 32% had disease linked to BRCA2." (PMID 31379942, 2019). "Eleven women with a positive family history previously underwent surgery for breast cancers, and in five cases BRCA1 (n = 4) or BRCA2 (n = 1), pathogenic alterations were detected in the ovary tumor samples." (PMID 31653094, 2019). "It is worth noting that PARPi has been currently confirmed for breast cancer therapy, which were clinically evaluated; on the other hand, olaparib has been also introduced for BRCA1/2 mutations carriers with HER2-negative metastatic breast cancer." (PMID 30975222, 2019). "In breast cancer cells with BRCA1/2 mutations, the administration of PARP1 inhibitors would largely destroy the repair of damaged DNA by blocking the homologous recombination repair pathway, eventually leading to cell death." (PMID 30890936, 2019). "The breast cancer cell line MDA-MB-436 is deficient in BRCA1 and generated SBS3 during in vitro culture accompanied by the characteristic deletions with microhomology and large numbers of rearrangements." (PMID 30849372, 2019). "A 35-year-old woman with a BRCA1 mutation developed DCIS as a primary breast cancer during surveillance, 12 years after genetic testing was performed." (PMID 30980249, 2019). "In BRCA1, some moderately penetrant variants have been identified, including p.Arg1699Gln (c.5096G>A), which has risk of breast cancer to age 70 of about 20%." (PMID 30832243, 2019). "The histone methyltransferase EZH2 is another candidate for intervention as it is overexpressed in BRCA1 normal breast tissue and implicated in mammary stem cell expansion as well as breast cancer." (PMID 31267556, 2019). "To assess the load of rare missense (VUS + pathogenic variants) variants in DNA-repair genes on the AAO of breast cancer in BRCA1-positive patients we performed a Burden test and a SNP-set (sequence) Kernel Association Test (SKAT-O)." (PMID 31395037, 2019). "We demonstrated that saliva from breast cancer patients with the BRCA1 mutation is characterized by increased antioxidant potential and a higher degree of oxidative damage to proteins and lipids." (PMID 31597313, 2019). "Studies have shown that the early termination of BRCA1 sequence translation can cause abnormal expression of BRCA1 protein, resulting in the development of breast cancer." (PMID 30968603, 2019). "Twenty‐five unrelated female patients diagnosed with familial breast cancer were screened for BRCA1/2 variants." (PMID 31131559, 2019).
breast cancer (continued). "BRCA1 sporadic mutations are also found in 1% of breast cancers, and the promoter can be hypermethylated in 11 to 14% of cases, resulting in BRCA1 gene inactivation." (PMID 31413819, 2019). "Some breast cancer-related BRCA1 missense mutations disturb the function of the BRCA1/BARD1 complex." (PMID 30975222, 2019). "This is relevant since luminal progenitors are the likely cell‐of‐origin for BRCA1‐mutated breast cancer, and the dysregulated levels of R‐loops seen in cancers lead to genomic instability (Aguilera & García‐Muse, 2012)." (PMID 31267556, 2019). "The BARD1 protein, which heterodimerizes with BRCA1, is encoded by a known breast cancer susceptibility gene." (PMID 30925164, 2019). "The pooled prevalence of BRCA1 mutation among Breast Cancer Patients was 11% (95% CI: 4–21%), and there was a substantial heterogeneity across the studies (Chi-square = 79.3, P value < 0.001, I-square = 87.38%)." (PMID 30898109, 2019). "The use of PARP (poly ADP ribose polymerase) inhibitor drugs for treating breast cancers or ovarian cancers with BRCA1/BRCA2 mutations is a widely documented example where synthetic lethality is used for effective treatment of cases with driver alterations." (PMID 31671773, 2019). "Here, we refined the spectrum of BRCA1/2 mutations and more precisely estimated the mutation frequencies including small-range mutations and LGRs in 539 early-onset and familial breast cancer patients from Pakistan." (PMID 31528241, 2019). "Compared to the general population, the risk of recurrence of contralateral breast cancer in patients with BRCA1/2 mutation increases by two to sixfold, and the younger the age at onset, the greater the risk of recurrence." (PMID 30968603, 2019). "This analysis identified a total of 80 breast cancers (~1.5%) with a homozygous deletion or an inactivating (putative) driver mutation in BRCA1." (PMID 30674894, 2019). "Currently, genetic testing for the risk of breast cancer is limited to the sequencing of BRCA1 gene for women with a history of breast cancer." (PMID 31046834, 2019). "In conclusion, our results show that some challenges exist in the early detection of breast cancers in BRCA1 or BRCA2 mutation carriers." (PMID 30980249, 2019). "Iterative mouse modeling and comparative oncogenomics analysis show that MYC-overexpression strongly reshapes the CNA landscape of BRCA1-deficient mammary tumors and identify MCL1 as a collaborating driver in these tumors." (PMID 30674894, 2019). "Accordingly, we showed in a multiple linear regression model that the enrichment of T cell-inflamed signature in BRCA1-deficient breast cancers can be attributed, at least in part, to these clinical features." (PMID 31022191, 2019). "Subsequently, populations of CD24+CD29+ cells and CD24+CD49f+ cells were isolated from BRCA1-mutated mammary tumors and displayed self-renewal and tumor-initiating capacity in vivo." (PMID 31619007, 2019). "We observed a 2.52 fold (53.8% vs. 21.3%) increased occurrence of BRCA1 mutations in breast and ovarian cancer families compared to breast cancer only families, in line with previous reports." (PMID 31528241, 2019). "Breast cancer type 1 and 2 susceptibility protein (BRCA1 and 2) are two vital components of this system, and genetic alterations of their encoded genes are commonly found in patients with hereditary breast and ovarian cancer syndromes." (PMID 31450627, 2019). "Hypoxia facilitated the enrichment of the CSC-like populations in both BRCA1-competent and BRCA1-deficient breast cancer cells." (PMID 31273285, 2019). "Approximately 15–40% of hereditary breast cancers occur due to pathogenic variants (PVs) of BRCA1 (17q21) and BRCA2 (13q12–13)." (PMID 31331294, 2019). "Increasing evidence suggests that BARD1 mutations is very likely to occur in patients with non-BRCA1/2 inherited breast cancer." (PMID 30975222, 2019).
breast cancer (continued). "The reason for delayed RRSO was that, in a significant number of breast cancer patients, BRCA1 mutation was diagnosed after diagnosis of breast cancer." (PMID 30918533, 2019). "PARP inhibitors, such as olaparib, are effective for the treatment of ovarian and breast cancers with deleterious BRCA1 or BRCA2 mutations." (PMID 31699977, 2019). "We examined the association between regular NSAID use and breast cancer risk using a large cohort of women selected for breast cancer family history, including 1054 BRCA1 or BRCA2 mutation carriers." (PMID 30999962, 2019). "Px was higher in patients with both breast cancer and the BRCA1 mutation compared to NZ (H = −4.246126, p = 0.0001), and slightly lower in PZ compared to NZ (H = −3.658388, p = 0.0004)." (PMID 31597313, 2019). "In this study, we aimed to analyze and report the clinical characteristics of breast cancer patients with BRCA1 L63X mutation, which is one of the BRCA1 founder mutations in the Japanese population, using the Japanese HBOC consortium trial registration data." (PMID 31143373, 2019). "A proportion of all breast cancers can be explained by the inheritance of germline mutations in one of the two major breast cancer susceptibility genes BRCA1 and BRCA2 related to DNA repair mechanisms." (PMID 30842790, 2019). "In a preclinical model of BRCA1-mutated breast cancer, the combination of a DNA-damaging agent, such as cisplatin, and immune checkpoint inhibitors (anti-CTLA4 and/or anti-PD-1) was found to be synergistic." (PMID 31336685, 2019). "In summary, BRCA1/2 pathogenic variants were found in 1.8% of an unselected Swedish breast cancer cohort." (PMID 30175445, 2019). "Genetic predisposition, such as breast cancer 1 (BRCA1) mutations, account for a minor percentage of the total breast cancer incidences." (PMID 31690802, 2019). "A variation in the 3 prime untranslated regions (3′-UTRs) affects the binding of microRNA (miRNA) to the breast cancer (BC) susceptibility gene 1 (BRCA1) gene, and thus regulate its expression." (PMID 31651107, 2019). "A number of countries other than Japan have previously conducted studies that demonstrated differences in histopathology and imaging characteristics between breast cancers associated with BRCA1 and BRCA2 mutations." (PMID 30820924, 2019). "Breastfeeding and its duration appear to have a protective effect against the risk of breast cancer, especially for women with mutations in predominantly the BRCA1 gene but also the BRCA2 gene." (PMID 33537600, 2019). "Breast Cancer susceptibility genes 1&2 (BRCA1&2) are tumor suppressor genes, involved in DNA-repair and cell cycling." (PMID 31489114, 2019). "Over the last two decades, discoveries related to the breast cancer susceptibility genes 1 and 2 (BRCA1 and BRCA2) have profoundly changed our understanding and management of hereditary breast and ovarian cancers." (PMID 30915162, 2019). "One such approach is using cell cycle checkpoint inhibitors such as WEE1 or Chk1 inhibitors in combination with DNA damaging agents (i.e., platinum) or PARP inhibitors in BRCA1 deficient breast cancer." (PMID 30993195, 2019). "Although PVs in several genes have been associated with an increased risk of breast cancer, two genes BRCA1 and BRCA2, appear to account for more cases of hereditary breast (and ovarian) cancer than the others." (PMID 30832243, 2019). "The odds ratio observed in this study indicates a potential effect of co-occurring DNA-repair truncating variants and pathogenic variants in BRCA1 on the earlier onset of breast cancer." (PMID 31395037, 2019). "Both CX-3543 and CX-5461 have advanced to clinical trials for pancreatic neuroendocrine tumor and BRCA1/2-deficient breast cancer, respectively." (PMID 30808951, 2019). "Owing to limited data regarding long-term outcomes, RANSM is performed only in highly selected patients, primarily patients with early breast cancer, healthy carriers showing BRCA1/2 mutation, and those with benign disease." (PMID 31666551, 2019).
breast cancer (continued). "Poly-ADP ribose polymerase inhibitors target BRCA1-deficient breast cancer cells which cannot represent triple negative breast cancers in general." (PMID 31636652, 2019). "This study would go further to identify a subgroup of patients that would likely respond to ZMCs, which is breast cancer patients that harbor BRCA1 mutations." (PMID 30993195, 2019). "Such an increase had been previously suggested in a publication showing that a BRCA1 deficient-like gene expression signature was higher in breast cancer BM." (PMID 31086113, 2019). "Aberrant progesterone/receptor activator of nuclear factor κβ (RANK) signaling has been implicated in BRCA1 breast cancer development." (PMID 31069010, 2019). "Fold changes in log2 of PD-1 expression for BRCA1-deficient breast cancers compared BRCA-proficient breast cancers from WSI and TCGA were 2.2 and 1.4, respectively." (PMID 31022191, 2019). "In breast cancer, the combination of olaparib and durvalumab resulted in an overall response rate of 63% (95% CI 44–80%) at 28 weeks in 30 patients with germline BRCA1/2 mutations." (PMID 31320901, 2019). "During the surveillance period, 5 individuals with BRCA1 or BRCA2 mutations were diagnosed with primary breast cancer." (PMID 30980249, 2019). "Germline mutations in BRCA1/2 are intensively studied in breast cancers, and TNBC is highly related to BRCA1 germline mutations and family history." (PMID 30630526, 2019). "Here, again, BRCA2 (3%) and BRCA1 (2.8%) were the most commonly mutated bona fide HR genes and predominantly seen in ovarian and breast cancers." (PMID 31921645, 2019). "Fifty-nine breast cancers met selection criteria; of these, 30 were BRCA1-associated tumors, and 29 were BRCA2-associated tumors." (PMID 30820924, 2019). "Women with a BRCA1 or BRCA2 pathogenic variant have a 50%‐80% risk of developing breast cancer and a 20%‐40% risk of developing ovarian cancer." (PMID 31531966, 2019). "PARP inhibitors represent an important advancement in the treatment of BRCA1 deficient breast cancers; however, resistance is now a well-recognized problem." (PMID 30993195, 2019). "Approximately 60 to 80% of breast cancer patients with BRCA1 germline mutations have triple negative cancers." (PMID 30962858, 2019). "According to the National Comprehensive Cancer Network guidelines and the Japanese Breast Cancer Society guidelines, annual MRI should be performed as part of regular check-ups for individuals with BRCA1 or BRCA2 mutations." (PMID 30980249, 2019). "The spectrum of BRCA1 gene mutations is different and has significant variation in their contribution to breast cancer in different population." (PMID 31759379, 2019). "In breast cancer, loss of BRCA1 results in dedifferentiation of mammary epithelial cells to a more stem cell like phenotype, with upregulation of CD44 and induction of EMT." (PMID 31213009, 2019). "BRCA1-mutated breast cancer is primarily driven by DNA copy-number alterations (CNAs) containing large numbers of candidate driver genes." (PMID 30674894, 2019). "The tumors which had been imaged by both mammography and MR were divided into 30 breast cancers in BRCA1 mutation carriers and 29 breast cancers in BRCA2 mutation carriers." (PMID 30820924, 2019). "It is difficult to identify cancer driver genes in cancers, for instance BRCA1 mutated breast cancer, that are characterised by large scale genomic alterations." (PMID 30674894, 2019). "This study aims to identify mutations in BRCA1–2 genes in women with familial breast cancer from different regions of Colombia." (PMID 31341521, 2019). "Fold changes in log2 of PD-L1 expression for BRCA1-deficient breast cancers compared BRCA-proficient breast cancers from WSI and TCGA were 1.2 and 0.68, respectively." (PMID 31022191, 2019).